IL2 (interleukin 2)
Diseases named in the same sentence as IL2 in open-access papers (continued):
Sharing a sentence is not in itself a finding about the gene and the disease.
infection (continued). "The therapeutic effect of MPX was evaluated in a murine model, revealing that MPX could protect against lethal infection with E. coli in mice and reduce the expression of the inflammatory factors IL-2, IL-6, and TNF-α, thereby alleviating intestinal inflammation." (PMID 34177825, 2021). "Therefore, despite several lines of evidence for Ld-IL2 therapy in maintaining the immunity to infection, a formal evaluation of how Ld-IL2 therapy might impact infections in autoimmune and inflammatory diseases is still lacking." (PMID 34618873, 2021). "After vaccination with H1-DDA/TDB, both IFN-γ+TNF+IL-2+ triple-positive and IFN-γ−TNF+IL-2+ double-positive multifunctional T cells can be detected > 1 year post-vaccination in spleens and peripheral blood and accumulate in the lungs of vaccinated mice after infection with Mtb." (PMID 34351501, 2021). "IL-2 is known to function by promoting the differentiation of immature T cells into effector and regulatory T cells which may positively affect the outcome of infection." (PMID 33028385, 2020). "Similarly, the proportion of infection-elicited TNFα+, IL2+ and polyfunctional CD4+ T-cells was significantly higher among influenza A/H3N2-infected (p = 0.038, 0.017 and 0.041 respectively) and influenza B-infected patients (p = 0.002, 0.048 and 0.004 respectively) than in vaccine recipients." (PMID 32572168, 2020). "Thus, the failure of the NK cell population to expand following infection could be a result of the preemptive expansion and consequent IL2 depletion by Tregs." (PMID 32111171, 2020). "It is also possible that the increased levels of IL5, which probably are due to both the infection and the increased levels of IL2, could contribute to an improved bacterial clearance as IL5 induces the production of eosinophils that could provide a survival benefit in S. aureus bacteremia." (PMID 32111171, 2020). "In the present study, IL-2 was assumed to influence, even at low serum levels, the self-limited evolution of clinical manifestations, culminating in the spontaneous resolution of infection in asymptomatic individuals —a role shared by IL-17, as previously discussed." (PMID 32966326, 2020). "Similarly, IL-2 have essential role in key immune response mechanisms where they directly impact the differentiation of T cells, effector T cells, and memory T cells, helping the immune system act against infection." (PMID 32725311, 2020). "We thus reasoned that IL-2 signals may have a greater impact on immune responses against heterosubtypic IAV infection than during primary responses against IAV where IL-2-producing CD4 T cells only reach the lung in significant numbers at 6 or 7 days post-infection." (PMID 31412088, 2019). "However, NOTCH signaling was required for infection-induced IL-2." (PMID 27080341, 2016). "Following restimulation at 7 days post-infection, a similar percentage of aPKC-deficient CD8+ T lymphocytes produced IFNγ and TNFα compared to wild-type control cells; however, the percentage of aPKC-deficient cells that were capable of producing IL-2 was reduced." (PMID 26765121, 2016). "The numerical loss of tTregs during infection may be also due to a lack of survival factors, such as IL-2." (PMID 26745276, 2016). "IL-2 can enhance host immunity and inhibit parasitic growth, inducing a Th1-type immune response; by contrast, IL-10 inhibits cytokine production by Th1 cells while exhibiting increased serum levels with infection progression, resulting in mainly Th2-type immune response." (PMID 26352932, 2015). "Our data also imply that CD4+ or CD8+ T cells—the major source of IL‐2 in most systems—may also play a role in amplifying NK‐cell responses and thus that IL‐2 production by memory T cells may represent an important effector response during re‐infection or after vaccination." (PMID 26420375, 2015).
infection (continued). "Our results suggest that the F1 domain, which contains the highest affinity epitope of the NH36 for CD8+ T cells, might be important for the development of CD8+ TCM cells, which through the high secretion of IL-2, or TNF or IL-2-TNF actively contribute to the cure of the established infection." (PMID 24966857, 2014). "Additionally, B. melitensis may not just subvert these immune effectors, but actively suppress the expression of IFN-γ and IL-2 at certain times over the course of infection." (PMID 22558103, 2012). "Post-hoc comparisons showed significantly elevated production of GM-CSF (P = 0.005), IL-2 (P = 0.008), and IL-5 (P = 0.03) in the chronic infection compared to uninfected groups and elevated production of IL-5 (P = 0.03) and IL-10 (P = 0.0008) in the chronic versus light infection groups." (PMID 21666788, 2011). "A possible explanation for this fact may be an inhibition of IL-2 or its receptor production in lymphocytes by the parasites: such strategy would limit the area of an immune response, allowing for dissemination of the infection." (PMID 21824434, 2011). "In addition, IL-2 is a key cytokine for the maintenance of regulatory T cells, which may show heightened activity in patent infection." (PMID 21039611, 2010). "The PB2/IL-2 cell line was established by in vitro infection with HTLV-1 of peripheral blood lymphocytes from a single healthy donor and continuous cell culture in the presence of the IL-2 growth factor for 12 months before frozen stockage." (PMID 41599396, 2026). "Overall, children developed a SARS-CoV-2–specific CD4+ T cell response early in the course of infection with multiple effector functions, marked by potent production of IFN-γ, TNF, and IL-2, and preferential expression of CXCR3." (PMID 40906527, 2025). "A Th1-mediated adaptive immune response plays a pivotal role in infection control by driving the production of cytokines such as IFN-γ, IL-2, and TNF-α." (PMID 41310729, 2025). "The question arises, on the one hand, about the mechanism in which L. rhamnosus influences increased levels of IL‐2 and IFN gamma and, on the other hand, how this is related to improved immunity to infection in the patients studied." (PMID 41190418, 2025). "On day three post-infection, cells were divided into two groups that were either treated with the combination of PHA/IL-2 latency reversing agents (LRA) or left untreated." (PMID 40372991, 2025). "Infection of BALB/c and STS mice resulted in 10-500× increase of production of IFNγ IL-2, IL-4, IL-6 and IL-10 by their splenocytes, whereas strain O20 splenocytes did not produce any of these cytokines except IL-6." (PMID 41164189, 2025). "Conversely, upon losing control of the infection, T cells would differentiate toward effector memory (TEM) cells with reduced IL-2 production and increased IFNγ and TNF secretion." (PMID 41159744, 2025). "Compared with the PBS + infection and CpG + infection groups, both the rEg.P29T+B + CpG + infection and rEg.P29 + CpG + infection groups exhibited significantly higher levels of IFN-γ, IL-2 and TNF-α." (PMID 40266142, 2025). "Our previous data indicated that after two vaccinations, 64% of the patients showed specific IFN-γ and/or IL-2 responses, and after MPXV infection all patients responded." (PMID 41012178, 2025). "After MPXV infection, specific T cells reached a median frequency of 15 IFN-γ and 10 IL-2 secreting cells per 300,000 PBMCs (0.005% and 0.003%, respectively)." (PMID 41012178, 2025). "To further investigate the antiviral mechanism of AVI-4206, we measured the abundance of the antiviral cytokines IP-10, IL-2, IL-6, and TNF-α in lung tissue at 4 and 7 days post-infection." (PMID 39149230, 2025). "To determine the influence of coexistent Ss infection on type 1, type 17, and proinflammatory cytokines in TBI, we measured the QFT supernatants levels of IFN-γ, TNF-α, IL-2, IL-17, IL-22, IL-1α and IL-1β in TBI+Hel+ and TBI+Hel- individuals." (PMID 41583474, 2025).
infection (continued). "From the perspective of the color scale, the expressions of IL-8, IL-1β, IL-4, IL-6, IL-2, TNF-α, IL-10, and IL-17 showed a significant upward trend as the infection duration increased." (PMID 41165313, 2025). "Four weeks post infection with M.tb HN878, we observed a significant increase in circulating IFN-γ, TNF-α, IL-1β, IL-2, IL-6, IL-12p70, IL-17A/F, IL-15, and IL-33 levels in mice immunized with ID93+EmT4TM compared to saline controls." (PMID 40285479, 2025). "On day three post-infection, cells were divided into two groups that were either treated with the combination of phytohaemagglutinin (PHA) and interleukin 2 (IL-2) latency reversing agents (LRA) or left untreated." (PMID 39829859, 2025). "Bov342 infection resulted in upregulation of CXCL1, whereas VN1203 resulted in IFN-γ, IL-2, IL-5, and IL-10." (PMID 40410375, 2025). "Animals that survived infection also had transiently increased levels of IL-1β, IFN-γ, IL-15, G-CSF, and IL-2, each of which returned to baseline at ≈10–14 d post-exposure, suggesting regulation of a systemic inflammatory response." (PMID 41460894, 2025). "IHC analysis revealed a significant increase in the expression of the cytokines TNF-α, IL-2, and IFN-γ in lung tissues of the RV group, suggesting a robust inflammatory response to the infection." (PMID 40266210, 2025). "After mpox infection, all patients showed specific IFN-γ secretion and 7 out of 10 (70%) IL-2 secretion." (PMID 38400115, 2024). "HIV-mediated activation of Jurkat cells was evidenced by increased mRNA levels of IL-2, CD25, and TGF-β, for those with higher infection levels; therefore, the subsequent experiments were conducted to study the impact of this condition on LX-2 cells." (PMID 38715844, 2024). "Like both SRF and IL-2, the transcription factor IRF4 is dispensable for initial CD8+ T-cell activation and proliferation during infection, but necessary for sustained expansion and SLEC proliferation." (PMID 39261466, 2024). "In previous studies, a single application or mixture of probiotics has shown the reduction of proinflammatory cytokines including IFN-γ IL1B, IL2, IL8, and TNF-α in various animal species and cell lines after pathogen-induced infection." (PMID 38561808, 2024). "On the other hand, peptides 3–6 showed an elevated subpopulation of CD44+ and IL-2+ within CD4+, and CD3+ populations after 4 days of infection." (PMID 38629077, 2024). "Nonetheless, they noted a moderate immune polarization on the Th1 side by the expression of IL-2, IL-12, IFN-γ, and transcriptional factors (STAT1 and STAT4) upon infection of dendritic cells with L. tarentolae expressing the SARS-CoV-2 full-length S." (PMID 39817166, 2024). "The most common infection site for bacterial infections was the urinary tract (N=73 in total; 44 in the ATG and 29 in the IL-2 RA group)." (PMID 39606231, 2024). "Their cytokine profile suggested a reduced ability to respond to SARS-CoV-2, with lower levels of IL-2, IL-4, IL-12p40, and IFN-γ, which are crucial for T-cell function and infection control." (PMID 39597537, 2024). "Leptin upregulates ROS production and inhibits the migration of the neutrophils.Leptin can increase the expression of inflammatory factors (IL-2, IL-12, and IFN-γ) in monocytes to induce a Th1-dominant immune response in infection." (PMID 39220365, 2024). "Specifically, there were 129 hospitalizations due to infections in patients who received induction therapy with ATG, compared to 100 cases in patients who received IL-2 RA as induction therapy." (PMID 39606231, 2024). "Compared with infection alone, levamisole and BMS-1 reduced IL-1β, IL-10, IL-18, TNF-α and IFN-γ mRNA expression and increased IL-2 and IL-8 mRNA expression (P < 0.01)." (PMID 39075562, 2024). "After infection, orthopoxvirus-specific T cells reached a median frequency of up to 21 IFN-γ and 8 IL-2 secreting cells per 300,000 PBMCs, depending on the cell culture conditions (0.0070% and 0.0027%, respectively)." (PMID 38400115, 2024).
infection (continued). "We here assessed the frequency of virus-specific T cells, secreting either the pro-inflammatory cytokine interferon (IFN)-γ or interleukin (IL)-2, and compared HIV-positive patients after vaccination and infection." (PMID 38400115, 2024). "In contrast, infection with the Omicron, yielded a slight increase in TNF-α secretion with less amount of IL-1β and Interleukin 2 (IL-2) compared to wild-type." (PMID 38568894, 2024). "H3N2-specific CD4+ T cells were predominantly IL-2 single producers, and this response was maintained over the course of H3N2 single infection (mean of 0.10%, 0.06%, and 0.09% at 14, 28, and 34 dpi, respectively)." (PMID 37287962, 2023). "More importantly, both SARS-CoV-2 and pCoV-GD01 infection induced the production of cytokines such as IFN-gamma, IL-12p70, IL-13, IL-2, IL-5, TNF-alpha, IL-17A, IP-10, MCP-3, MIP-1beta, MIP-2, Exotaxin, IL-15/15R, IL-28, IL-3, G-CSF, IL-1alpha and ENA-78." (PMID 37330497, 2023). "The pro-inflammatory cytokines (Th1 immune response) (IL-1, IL-2, IL-6, IL-8, IL-18, IFN-γ, and TNF-α) generally regulate growth, cell activation, differentiation, and homing of the immune cells to the infection sites." (PMID 38133693, 2023). "Consistent with IFN-γ ELISpot assay results, the frequencies of IFN-γ, TNF, and IL-2 single, double, and triple producers within the CD4+ and CD8β+ T-cell subsets were overall low after H3N2 single infection (mean < 0.5%)." (PMID 37287962, 2023). "Prior to infection, the disease protective latent condition presented the cytokine panel with mild or moderate levels of TNF-α, IFN-γ, IL-2, IL-17, and IL-6." (PMID 36646786, 2023). "Concentrations of IFN alpha and IL-8 increased gradually over the course of infection, whereas levels of IFN gamma, IL-2 and TNF alpha were relatively stable until day 9 post-infection at which point dramatic increases were observed." (PMID 36992478, 2023). "CD4+ and CD8+ T cells curtail the infection by the production of IFN-γ, tumor necrosis factor alpha, and IL-2 as well as by direct cytotoxicity or lysis of infected cells." (PMID 37903443, 2023). "There was a significant increase in in the secretion of cytokines IL-2, IL-6, IL-10, TNF-α, and IFN-γ in the H3N2 virus-infected group 24 hours after infection." (PMID 37900310, 2023). "The HLA-A11/DR1 mice strain induced lower levels of several cytokines (IL-2, IL-10, IL-18, IL-1β, TNF-α, IL-1α, IL-28, and ENA78), but showed increased secretion of IFN-γ, RANTES, IP10, and Eotaxin at 12 h post-infection, compared to the WT group." (PMID 38035330, 2023). "After natural infection with B. contaminans, the proportion of TNF-α/IL-2 double-producing and TNF-α/IFN-γ/IL-2 triple-producing DP T cells increased significantly." (PMID 36960295, 2023). "Regarding L. infantum, the control of infection requires the activation of T helper 1 (Th-1) cells, which increases the IFN-γ and IL-2 serum levels." (PMID 36759910, 2023). "The percentages of IFN‐γ+ cells that were also expressing IL‐2 and/or TNF were the same before and at day 5, and day 35 following re‐infection." (PMID 37490492, 2023). "Th1 immune response is mainly induced upon intracellular pathogen infection and generally produces IFN-γ, IL-2, TNF-β, etc., which are critical for macrophage activation and eliciting cell-mediated immunity." (PMID 36986643, 2023). "The adaptive response characterized by T-helper 1 (Th1) activation produces cytokines such as interferon-gamma (IFN-γ), interleukin-2 (IL-2), and tumor necrosis factor-alpha (TNF-α), which help to control the infection." (PMID 37375511, 2023). "Pathogen-associated specific CD8+T cells, which produce high levels of IL-2, IFN-γ, TNF-α, perforin, and granzyme B to regulate the infection, are essential for HCMV immunity." (PMID 36723437, 2023).
infection (continued). "The levels of IL-12p70, MCP-1, IL-10, IL-1β, IFN-γ, IL-2, M-CSF, VEGF, ICAM-1, and P-selectin increased after infection; however, the expression of all except MCP-1, IFN-γ, and P-selectin was strongly suppressed by anti-TNF-α Ab treatment." (PMID 37939119, 2023). "Early after infection, we also observed the presence of polyfunctional memory CD4+ T cells capable of producing, simultaneously, IL-2 and IFN-γ." (PMID 38006037, 2023). "The numbers of multifunctional cytokine+ CD4 T cell that produced IFN‐γ, IL‐2 and TNF were particularly stable between days 9 and 30 post‐infection." (PMID 37490492, 2023). "Our study revealed top 8 cytokines (IL-17, IL-1α, IL-2, IL-10, IL-5, IFN-γ, TNF-α and IL-6) and their biomarker abilities to discriminate different stages of infection." (PMID 36646786, 2023). "Th1‐like immune response usually determines a resistant profile, leading to subclinical infection or mild to moderate disease, involving cytokines such as IFN‐γ, IL‐2, and TNF‐ α." (PMID 38053473, 2023). "In the case of a clinically evident infection, there is a local immune response involving CD8+ cytotoxic T lymphocytes and T helper 1 CD4+, which produce interleukin 2 (IL-2) and interferon gamma (IFN-gamma) and recognize the viral protein E6, E7, and E2." (PMID 36851321, 2023). "Influenza-virus-specific CD4+TRMs in mice were shown to produce IL-2 and IFN-γ in the lungs upon infection and protect mice from lethal H1N1 virus challenge." (PMID 36851616, 2023). "First, vaginal LCs were exposed to HIV-1 for 2 days, allowing productive infection of LCs, then washed extensively and subsequently co-cultured with PHA/IL2-activated CD4 T cells in a 1:2 ratio for 3 days." (PMID 36841916, 2023). "Initially, a Th1 response dominates, characterized by elevated levels of interleukin-2 (IL-2) and interferon-gamma (IFN-γ), persisting until the egg-laying phase (approximately 5 weeks after infection)." (PMID 38203591, 2023). "First, we monitored total infection with R5/X4 HIV-GKO (csGFP+/mKO2+, csGFP+/mKO2−, and mKO2+/csGFP−) over 7 days, in primary CD4+ T cells stimulated with IL-2 or IL-15 at equimolar concentration." (PMID 35499323, 2022). "We stimulated CD4+ T cells from three different donors with equimolar concentrations of IL-2 and IL-15 and analyzed the expression of CDK9 and cyclin T1 after 8 to 9 days of stimulation, a time when latent and productive infection with HIV-GKO was measured." (PMID 35499323, 2022). "According to a previous study published in 1997, the authors found that IFN-γ, IL-2, IL-3, IL-4, and IL-5 were significantly changed in BALB/c mice after infection with a small amount of H. nana (100 eggs/mouse) at 14 days." (PMID 35878385, 2022). "IL-2, FGF, IFN-γ, and MCP-1 reached their highest levels within the second week of infection and then decreased." (PMID 36148228, 2022). "The levels of IL-2 were increased in the 40 mM and 80 mM L-GSH-treated animals, compared to the untreated group, at 2- and 8-weeks post-infection, although a significant difference was noted only for the 80 mM L-GSH treatment at 2 weeks." (PMID 35453358, 2022). "Magnitudes of post-infection IFN-γ and IL2 responses to the N+M pool were significantly correlated with IFN-γ and IL2 responses to the N and M pools." (PMID 35390102, 2022). "Significant correlation (using Spearman Rank Correlations) was observed between maximum post-infection IFN-γ and IL2 responses to the N+M pool and the N pool and the M pool." (PMID 35390102, 2022). "SARS-CoV-2-spike-specific T cells are characterized by significant interleukin-2 (IL-2) production, with tumor necrosis factor (TNF) also produced early after natural infection." (PMID 36075216, 2022). "Among them, IL-2, FGF, IFN-γ, and MCP-1 reached their highest levels within the second week of infection and then decreased." (PMID 36148228, 2022). "Using our previously established mouse infection model, we determined the viral replication with IFN-γ and IL-2 levels in vivo." (PMID 36366463, 2022).